DKK2 (dickkopf Wnt signaling pathway inhibitor 2)
Diseases named in the same sentence as DKK2 in open-access papers (continued):
Sharing a sentence is not in itself a finding about the gene and the disease.
hepatocellular carcinoma (3 papers, 2016 to 2020). A malignant tumor that arises from hepatocytes. "In contrast, Dkk2 deficient animals showed moderate hepatocellular atypia with anisocytosis–caryosis and nuclear hyperchromasia and developed hepatocellular carcinomas with loss of trabecular architecture resembling typical DEN induced liver tumors." (PMID 25826080, 2016). "Our results for patients after a primary resection are consistent with previous studies for gastric, colon, breast and hepatocellular carcinoma, where DKK2 was found as a tumor suppressor and its loss is associated with activation of the Wnt-pathway and consecutive tumor progression." (PMID 32075129, 2020).
intestinal tumor (3 papers, 2013 to 2026). "Consistently, the expression of Dkk2 was decreased in the intestinal tumors from Nat10cKO mice." (PMID 41542770, 2026). "In our previous study, we uncovered the function of DKK2 in promoting tumor progression by suppressing NK cell and CD8+ T cell activation in ApcMin/+ mouse intestinal tumor model." (PMID 32559853, 2020).
Osteopenia (3 papers, 2010 to 2018). Osteopenia is a term to define bone density that is not normal but also not as low as osteoporosis. "Dkk2-/- mutant mice are characterized by low bone density and osteopenia." (PMID 30035713, 2018). "First, while mice lacking one allele of Dkk1 display the expected high bone mass phenotype, Dkk2-deficient mice are characterized by reduced bone formation and osteopenia, thereby demonstrating that these two Krm2 ligands do not mediate the same effects on osteoblasts in vivo." (PMID 20436912, 2010). "The involvement of Dkk2 in regulating bone development was recently demonstrated when it was shown that knockout mice lacking Dkk2 developed osteopenia." (PMID 20843343, 2010).
prostate carcinoma (3 papers, 2020 to 2022). A carcinoma that arises from epithelial cells of the prostate gland. "DKK2 is also reported to be upregulated in prostate cancer, however, the sample size and tumor stage assessed are unclear." (PMID 35204808, 2022). "DKK2 gene amplification and homozygous deletion are rare in prostate cancer, with gene amplification being slightly more frequent in metastatic cases (primary: 0–0.7% and 0.3–0.4% respectively, metastatic: 1.4–1.8% and 0–0.7% respectively)." (PMID 35204808, 2022). "In human prostate cancer cells, DKK2 depletion is reported to suppress cell proliferation and invasion, attributable to reduced β-catenin and Wnt transcriptional targets CyclinD1 and Myc." (PMID 35204808, 2022). "For instance, DKK2 facilitated Wnt/β-catenin pathway and contributed to prostate cancer cells proliferation and invasion." (PMID 34364402, 2021).
Anxiety (2 papers, 2023 to 2025). Intense feelings of nervousness, tension, or panic often arise in response to interpersonal stresses. "Particularly, the role of gene-environment interactions in understanding anxiety risks is critical, with genetic variants like DKK2 and ATXN1 showing interactions with CS." (PMID 40125487, 2025). "GWEIS revealed multiple suggestive genes interacted with birth by CS for anxiety, such as DKK2 (rs13137764, P = 1.24 × 10− 9, adjusted P = 2.68 × 10− 7) and ATXN1 (rs62389045, P = 4.38 × 10− 8, adjusted P = 3.55 × 10− 6)." (PMID 37029353, 2023). "DKK2 plays a role in Wnt signaling, influencing neurodevelopment and synaptic plasticity, although its direct effects on anxiety remain unclear." (PMID 40125487, 2025). "Recent GWAS have also identified seven significant genetic loci—RNU6–168P, MAT2B, DKK2, DIP2C, COL22A1, OR4L1, and ATXN1—that influence anxiety traits in Caesarean-born offspring." (PMID 40125487, 2025). "DKK2 rs13137764, P = 1.24 × 10− 9, adjusted P = 2.68 × 10− 7; rs13148189, P = 1.34 × 10− 9, adjusted P = 2.83 × 10− 7) and ANTX1 were observed as significant genes for anxiety." (PMID 37029353, 2023).
cardiac hypertrophy (2 papers, 2022 to 2023). "METTL3 positively regulates PRI-MIR221/222 maturation in an M6A-dependent manner and subsequently promotes Ang-II-induced cardiac hypertrophy by inhibiting DKK2 activation of Wnt/β-catenin signaling." (PMID 36959563, 2023). "Subsequently, DKK2 was inhibited to explore its function in miR-221/222 regulating cardiac hypertrophy." (PMID 35836108, 2022). "Our findings suggest that METTL3 positively modulates the pri-miR221/222 maturation process in an m6A-dependent manner and subsequently activates Wnt/β-catenin signaling by inhibiting DKK2, thus promoting Ang-II-induced cardiac hypertrophy." (PMID 35836108, 2022). "However, whether DKK2 is a participator in cardiac hypertrophy is still unclear." (PMID 35836108, 2022).
colitis (2 papers, 2024). Inflammation of the colon. "This is consistent with our previous report that DKK2 enhanced Lgr5 expression in colitis-induced cancer cells via HNF4α1, an isoform of HNF4A." (PMID 38659853, 2024).
hemangioma (2 papers, 2022 to 2023). A benign vascular lesion characterized by the formation of capillary-sized or cavernous vascular channels. "Specifically, M2 macrophage-derived exosomes deliver miR-27a-3p to hemangioma stem cells, reducing their sensitivity to propranolol by targeting dickkopf-related protein 2 (DKK2)." (PMID 37981718, 2023). "In addition, M2-sEVs can contain high levels of miRNA-27a-3p and deliver it to hemangioma stem cells to inhibit their sensitivity to propranolol in infantile hemangioma (IH) by downregulating dickkopf-related protein 2 (DKK2)." (PMID 35832790, 2022).
Insulin resistance (2 papers, 2019 to 2023). Increased resistance towards insulin, that is, diminished effectiveness of insulin in reducing blood glucose levels. "Low expression of the WNT inhibitor DKK2 is responsible for fat accumulation in obesity, but this gene may be responsible for the improvement of insulin resistance." (PMID 30678306, 2019). "Obese subjects with insulin resistance (higher HOMA-IR and lower oral glucose insulin sensitivity index) had higher expressions of DKK1, DKK2, sclerostin, and sFRP-1 but lower expression of osteogenic microRNA and β-catenin." (PMID 37569816, 2023).
liver cancer (2 papers, 2016). An epithelial or non-epithelial malignant neoplasm that arises from the liver. "These genes were closely linked to liver cancer before and thus a) demonstrated the close linkage of Dkk2 loss dependent genetic changes to liver cancer b) a functional impact of Dkk2 loss on many diverse genes and genetic networks." (PMID 25826080, 2016). "Our work now provides definite in vivo evidence that genetic loss of Dkk2 contributes to hepatocarcinogenesis and prognosis of patients with liver cancer." (PMID 25826080, 2016). "To dissect in more detail the underlying molecular mechanisms involved in an increased liver cancer development of Dkk2−/− animals, we performed microarray gene expression analysis of untreated livers from 4 Dkk2−/− and 4 WT animals to identify differentially regulated genes at 9 months of age." (PMID 25826080, 2016). "DEN treatment of Dkk2−/− KO mice resulted in a significantly increased liver cancer development compared to DEN treated WT mice." (PMID 25826080, 2016). "Another key finding of our study is the prognostic implication of the identified Dkk2 signature for human liver cancer." (PMID 25826080, 2016). "Dkk2 deletion results in alterations of liver morphology leading to an increased frequency of liver cancer." (PMID 25826080, 2016). "As a result we could attribute a key role for Dkk2 in preventing liver cancer development by interacting with WNT/β-catenin as well as other key oncogenes." (PMID 25826080, 2016). "The results from the functional analysis using cultured liver cancer cell support the hypothesis that DKK2 acts through the canonical Wnt pathway and antagonize the cell proliferation elicited by the Wnt3a ligand." (PMID 27203079, 2016). "Furthermore, the role of Dkk2 for liver cancer development was completely unknown." (PMID 25826080, 2016).
Neurodegeneration (2 papers, 2023). Progressive loss of neural cells and tissue. "In summary, the difference in microglial expression of the DAM/ARM gene DKK2 between mouse models and human AD brain highlights the increasingly recognized limitations of using mouse models to recapitulate facets of human neurodegenerative disease." (PMID 36599670, 2023). "Increasingly, however, limitations to the validity of mouse models to recapitulate human neurodegenerative disease have become apparent, as evidenced by the present study by the difference in microglial DKK2 expression between AD mouse models and human AD brain." (PMID 36599670, 2023). "As upregulation of DKK2 was not confirmed in human brains, the authors highlighted the limitations of relying solely on animal models to understand human neurodegenerative diseases." (PMID 38132144, 2023). "The potential to produce Dkk2+ ARM may further by influenced by other factors, which should be addressed in future studies, as different neurodegeneration disease models and CNS regions analyzed in our study exhibited varying contributions of Dkk2+ microglia relative to the total microglial pool." (PMID 36599670, 2023).
non-small cell lung carcinoma (2 papers, 2019 to 2023). A group of at least three distinct histological types of lung cancer, including non-small cell squamous cell carcinoma, adenocarcinoma, and large cell carcinoma. "This study aimed to investigate the potential of applying anti-DKK2 antibody to non-small cell lung cancer with APC mutations." (PMID 31372243, 2019).
Obesity (2 papers, 2019 to 2025). Accumulation of substantial excess body fat. "Previous literature has reported that DKK2 can act as an adipokine and has an inhibitory effect on the development of obesity, and the suppression of DKK2 expression may further promote the development of obesity, which is consistent with our clinical observation results." (PMID 40340623, 2025).
osteoporosis (2 papers, 2020 to 2022). A condition of reduced bone mass, with decreased cortical thickness and a decrease in the number and size of the trabeculae of cancellous bone (but normal chemical composition), resulting in increased fracture incidence. "Mesenchymal stem cell-derived EVs inhibit osteoporosis via microRNA-27a-induced inhibition of DKK2-mediated Wnt/β-catenin pathway." (PMID 36388171, 2022). "Taken together, Dkk2 might be a target for the development of a therapeutic drug for both sarcopenia and osteoporosis due to disuse." (PMID 32268570, 2020).
pancreatic cancer (2 papers, 2019). "We also investigate the impact of DKK2 on pancreatic cancer cells and status of immune cell infiltration." (PMID 31583260, 2019). "It is still unknown whether DKK2 plays similar roles in other cancer types with reoccurring APC mutations, such as pancreatic cancer." (PMID 31372243, 2019).
pancreatic ductal adenocarcinoma (2 papers, 2019 to 2021). An infiltrating adenocarcinoma that arises from the epithelial cells of the pancreas. "Our work suggested that DKK2 imparts tumor immune evasion and is associated with poor prognosis in pancreatic ductal adenocarcinoma." (PMID 31583260, 2019).
psoriasis (2 papers, 2012 to 2020). An autoimmune condition characterized by red, well-delineated plaques with silvery scales that are usually on the extensor surfaces and scalp. "Likewise, the downregulation of the canonical wnt inhibitor DKK2, CTNNBIP1 (ICAT), Axin2, as well as FRZB (SFRP3) is common to SCC and psoriasis." (PMID 22384081, 2012).
amyotrophic lateral sclerosis (1 paper, 2023). Amyotrophic lateral sclerosis (ALS) is a neurodegenerative disease characterized by progressive muscular paralysis reflecting degeneration of motor neurons in the primary motor cortex, corticospinal tracts, brainstem and spinal cord. "Having demonstrated microgliosis and clustering of Dkk2+ microglia around βAmyloid plaques in two different widely used AD mouse models, we next investigated whether our findings could be recapitulated in another neurodegeneration mouse model, the SOD1G93A amyotrophic lateral sclerosis (ALS) mouse." (PMID 36599670, 2023).
anemia (1 paper, 2021). A reduction in the number of red blood cells, the amount of hemoglobin, and/or the volume of packed red blood cells. "Ctnnb1OE-SEC BM-SEC reveal aberrant sinusoidal differentiation with altered EC gene expression and perisinusoidal ECM deposition and angiocrine dysregulation with de novo endothelial expression of FGF23 and DKK2, elevated in anemia and involved in vascular stabilization, respectively." (PMID 34845225, 2021). "The Wnt signaling pathway and its downstream angiocrine target molecules such as FGF23 and DKK2 may also bear therapeutic potential in various types of anemia or in hematopoietic neoplasms." (PMID 34845225, 2021).
Anorexia (1 paper, 2024). Lack of desire to eat (loss of appetite). "However, to our knowledge, the association of DKK2 with NVP symptoms such as anorexia has not been reported." (PMID 38509478, 2024).
breast tumor (1 paper, 2017). "IPP6.0 analysis showed that DKK2 protein expression was significantly lower in breast tumors (0.201 ± 0.038) than that in surgical-margins (0.274 ± 0.049) (***p < 0.001)." (PMID 28467796, 2017). "Our results also showed that ectopic expression of DKK2 can induce apoptosis, suppress cell growth, and halt cell cycle in G0/G1 in breast tumor cell lines, in agreement with previous reports." (PMID 28467796, 2017). "Our results showed that the restored expression of DKK2 in breast tumor cell lines significantly down-regulated active β-catenin." (PMID 28467796, 2017). "Here, DKK2 promoter methylation was detected in 77.8% (7/9) of breast cell lines and in 86.7% of breast tumor samples." (PMID 28467796, 2017). "Ectopic expression of DKK2 changed breast tumor cell morphology, inhibited cell proliferation and colony formation by inducing G0/G1 cell cycle arrest and apoptosis, and suppressed tumor cell migration by reversing epithelial-mesenchymal transition (EMT) and downregulating stem cell markers." (PMID 28467796, 2017). "As cell with stem cell properties is closely related to EMT for tumor cells, it is necessary to investigate whether DKK2 could negatively regulate cell stemness in breast tumor cells." (PMID 28467796, 2017). "However, DKK2 can be a new biomarker for early assessment of breast tumor." (PMID 28467796, 2017).
cardiac ischemia (1 paper, 2021). "In addition, injection of DKK2, an antagonist of Wnt signaling, binding to LRP5 and LRP6, was shown to be beneficial for infarct healing in a cardiac ischemia/reperfusion model." (PMID 34205318, 2021).
cervical cancer (1 paper, 2022). A primary or metastatic malignant neoplasm involving the cervix. "DKK2 epigenetic changes of DKK2 may play a key role in the development of cervical cancer, suggesting that DKK2 hypermethylation could be used as a triage test for screening, early diagnosis, or risk prediction of cervical cancer." (PMID 37551167, 2022). "DKK2 epigenetic changes may play a key role in the development of cervical cancer, suggesting a potential value of DKK2 hypermethylation as a triage test for screening, early diagnosis, or predicting the risk of cervical cancer." (PMID 37551167, 2022). "In the present study, we investigated DKK2 expression profiles and epigenetic alterations in cervical cancer." (PMID 37551167, 2022). "The present study indicated that among HR-HPV-positive cervical cancer patients, the methylation rate of DKK2 in HPV16/18-positive patients was more greatly enhanced than that in HPV16/18-negative patients." (PMID 37551167, 2022). "The positive rate of DKK2 mRNA expression in cervical cancer decreased significantly compared to that in HSIL (χ2 = 5.999, P = 0.014)." (PMID 37551167, 2022). "DKK2 mRNA expression was reduced in cell lines of cervical cancer and cancer tissues, whereas DKK2 hypermethylation was upregulated." (PMID 37551167, 2022). "MSP analysis was then performed to confirm the overall frequency of DKK2 methylation in cervical cancer." (PMID 37551167, 2022). "The real-world screening value of DKK2 methylation detection for cervical cancer needs further population-based research and discussion." (PMID 37551167, 2022). "DKK2 mRNA expression was downregulated in all cancer cell lines and cervical cancer tissues, whereas hypermethylation of DKK2 was higher in cervical cancer tissue samples." (PMID 37551167, 2022). "Here, we evaluated the mRNA expression profiles of DKK2 and its epigenetic alterations in cervical cancer cell lines and in samples from patients with cervical cancer." (PMID 37551167, 2022). "The rate of detection of DKK2 methylation in HPV16/18-positive patients in the cervical cancer group (66.7%) was significantly higher than that in HPV16/18-negative patients (36.0%) (χ2 = 6.279, P = 0.015)." (PMID 37551167, 2022). "In the present study, RT-PCR showed reduced expression of DKK2 mRNA in cervical cancer compared with either normal cervical samples or HSIL samples." (PMID 37551167, 2022). "Among 79 cervical cancer samples analyzed, only 25 of 79 (31.6%) showed DKK2 mRNA expression." (PMID 37551167, 2022). "In addition, DKK2 mRNA expression was restored after 5-Aza-dC treatment of cell lines of cervical cancer." (PMID 37551167, 2022). "Collectively, the data demonstrate that DKK2 is predominantly methylated in cervical cancer." (PMID 37551167, 2022). "DKK2 promoter hypermethylation was detected in 41 of 79 cases (51.9%) of cervical cancer tissues." (PMID 37551167, 2022). "We then examined DKK2 mRNA expression both in cervical cancer cell lines and in tissue samples." (PMID 37551167, 2022). "DKK2 methylation in cervical cancer was significantly higher than that in HSIL (χ2 = 8.346, P = 0.004), whereas DKK2 methylation in HSIL was significantly higher than that in normal cervical samples (χ2 = 7.934, P = 0.005) and in LSIL samples (χ2 = 4.375, P = 0.037)." (PMID 37551167, 2022). "Further, through MSP analysis DKK2 is found to be methylated in most patients diagnosed with cervical cancer, while it is not in HSIL and normal cervical samples." (PMID 37551167, 2022). "Positive DKK2 mRNA expression in cervical cancer cases without methylation (47.4%) was significantly higher than that of cervical cancer tissues with promoter hypermethylation (17.1%) (χ2 = 8.368, P = 0.002)." (PMID 37551167, 2022). "Although DKK2 plays a significant role in many tumors, its correlation with clinicopathological characteristics such as lymph node metastasis and HPV infection is still unknown in cervical cancer." (PMID 37551167, 2022).
cervical metaplasia (1 paper, 2021). Metaplastic changes in the cervical glandular or squamous epithelium. "Using a mouse model of cervical metaplasia, we further show that the endocervical stroma undergoes remodelling and increases expression of the Wnt inhibitor Dickkopf-2 (DKK2), promoting the outgrowth of ectocervical stem cells." (PMID 33462395, 2021).
clear cell carcinomas (1 paper, 2021). "Dkk2 expression differed significantly between the histological cancer subtypes with clear cell carcinomas showing the highest median IRS of 12 compared to the other subtypes (range: 9–12; p<0.001)." (PMID 33679613, 2021). "Highest Dkk2 expression of all subtypes was observed in clear cell carcinoma." (PMID 33679613, 2021). "Clear cell carcinoma exhibited the highest Dkk2 expression at all and LGSC showed significantly higher expression compared to the other histologies, which could reflect the different pathogenesis and origins of the histological subtypes." (PMID 33679613, 2021).
COVID-19 (1 paper, 2022). A disease caused by infection with severe acute respiratory syndrome coronavirus 2. "We compared the proportion of entry factor genes in Lymphatic ECs, EndMT, DKK2+ ECs, activated ECs, and rest ECs in COVID-19 and IPF." (PMID 36248845, 2022).